FHIT (fragile histidine triad diadenosine triphosphatase)
Diseases named in the same sentence as FHIT in open-access papers (continued):
Sharing a sentence is not in itself a finding about the gene and the disease.
mastitis (3 papers, 2023 to 2024). Inflammation of breast tissue during lactation or postpartum due to an obstructed duct or infection. "Meanwhile, the expression of the FHIT gene was significantly higher in the blood from the healthy group compared to the mastitis group." (PMID 37372369, 2023). "The expression of the FHIT gene was reduced in Xinjiang brown cattle with mastitis, and gene expression levels were negatively correlated with methylation levels of the FHIT gene promoter." (PMID 37372369, 2023). "Finally, we selected the PIAS1 and FHIT genes and further investigated their effect on mastitis in terms of epigenetics." (PMID 37372369, 2023). "Hence, increased methylation in the promoter of the FHIT gene reduces the mastitis resistance in Xinjiang brown cattle." (PMID 37372369, 2023). "The decrease in the methylation level in the promoter region of the FHIT gene may enhance resistance to mastitis in Xinjiang brown cattle." (PMID 37372369, 2023). "In a word, we consider that hypermethylation of the FHIT gene promoter region may lead to the suppression or reduction in FHIT gene expression, inhibiting its transcriptional activity and affecting the occurrence and development of mastitis." (PMID 37372369, 2023). "The results further show that the methylation level of the CpG6 site of the FHIT gene promoter was higher in the healthy group, higher than that in the mastitis group, and the methylation levels of CpG3, CpG5, and CpG8 sites were significantly higher in the mastitis group (p < 0.01)." (PMID 37372369, 2023). "Further analysis showed that the methylation levels of the FHIT and PIAS1 genes were higher in the mastitis group than in the healthy group." (PMID 37372369, 2023). "Meanwhile, the methylation levels of CpG3, CpG5, CpG8, and CpG15 in the promoter region of the FHIT and PIAS1 genes in the mastitis group were significantly higher than those in the healthy group (p < 0.01), respectively." (PMID 37372369, 2023). "RT-qPCR showed that the expression levels of the FHIT and PIAS1 genes were significantly higher in the healthy group than those in the mastitis group (p < 0.01)." (PMID 37372369, 2023). "Pyrosequencing analysis showed that the promoter methylation levels of the FHIT and PIAS1 genes in the mastitis group were higher and lower, respectively, than those in the healthy group (65.97 ± 19.82% and 58.00 ± 23.52%)." (PMID 37372369, 2023). "Changes in the promoter methylation levels of FHIT and PIAS1 may influence the expression of these genes to further regulate the development of mastitis." (PMID 37372369, 2023). "Finally, we consider that the methylation of the FHIT and PIAS1 genes affects the expression of the genes to a certain extent and can be used as an epigenetic marker for mastitis resistance in Xinjiang brown cattle." (PMID 37372369, 2023). "The results of RT-qPCR showed that the FHIT and PIAS1 genes were expressed in the blood of cattle in the healthy and mastitis groups, and the expression levels of both genes were significantly higher in blood from healthy cattle than those with the mastitis group (p < 0.01)." (PMID 37372369, 2023).
renal carcinoma (3 papers, 2004 to 2022). A carcinoma arising from the epithelium of the renal parenchyma or the renal pelvis. "Hypermethylation on cfDNA was detected for the LRRC3B (74.1%), APC (51.9%), FHIT (55.6%), and RASSF1 (62.9%) genes in patients with renal cancer." (PMID 27725787, 2016). "The low occurrence of terminal deletions encompassing the FRA3B region in nonpapillary RCC (3 from 100) or normal FHIT transcripts in renal cancer cell lines lead to the conclusion that FRA3B/FHIT is not involved in the development of nonpapillary RCC." (PMID 35445830, 2022). "The results obtained indicate that the concentration of cell-free DNA in plasma and the methylation of specific genes (such as FHIT, APC, and RASSF1) can be a significant addition to serological tumor markers in the identification of patients with renal cancer." (PMID 27725787, 2016).
acute lymphoblastic leukemia (2 papers, 2013 to 2021). Leukemia with an acute onset, characterized by the presence of lymphoblasts in the bone marrow and the peripheral blood. "The aim of the present study was to analyze the expression of WW-domain oxidoreductase (WWOX), fragile histidine triad (FHIT) and p73 in acute lymphoblastic leukemia (ALL)." (PMID 24137446, 2013).
alcohol dependence (2 papers, 2012 to 2025). Physical and psychological dependence on alcohol. "Also noteworthy is that SH3GL2 and FHIT, two of the clock modulator genes that are both illness-associated and lithium-responsive, are located within two chromosomal areas (9p22.2 and 3p14) associated with comorbid BD and alcoholism." (PMID 22384149, 2012).
Barrett esophagus (2 papers, 2014 to 2026). Esophageal lesion lined with columnar metaplastic epithelium which is flat or villiform. "FHIT, WWOX span fragile sites (FRA3B and FRA16D) that are frequently mutated in precursor lesions to EAC, including Barrett's esophagus and Barrett's associated dysplasia." (PMID 24454681, 2014).
cervical (2 papers, 2002 to 2010). "The poor performance of 3p14 in high-grade dysplasia and excellent performance in cancer leads us to believe that the loss of 3p14 locus, which comprises the FHIT gene, is a late event in cervical disease." (PMID 20712890, 2010).
chordoma (2 papers, 2011 to 2022). Chordomas are rare malignant tumors arising from embryonic remnants of the notochord in axial skeleton. "This region contains multiple genes, including RBM5, FHIT and PTPRG, but their involvement in chordoma pathogenesis has yet to be determined." (PMID 22613809, 2011). "Despite the identification of numerous genes with dysregulated expression in vitro or in vivo in chordoma (e.g. brachyury, EGFR, Ezrin, MMP-9, c-MET, FHIT, etc.) conventional or targeted chemotherapeutic agents showed a partial response at best-case scenarios in clinical case-series." (PMID 36033338, 2022).
clear cell renal carcinoma (2 papers, 2016 to 2021). A malignant epithelial neoplasm of the kidney characterized by the presence of lipid-containing clear cells within a vascular network. "Previously, a significant correlation between FHIT expression in clear cell renal carcinomas and patient survival was demonstrated." (PMID 27725787, 2016).
colorectal tumors (2 papers, 2019 to 2022). "For example, low levels of FHIT and increased levels of a target of MIR7515, c-MET, have been linked to increased risk of metastasis of colorectal tumors." (PMID 30738427, 2019).
Crohn disease (2 papers, 2020 to 2023). A gastrointestinal disorder characterized by chronic inflammation involving all layers of the intestinal wall, noncaseating granulomas affecting the intestinal wall and regional lymph nodes, and transmural fibrosis. "Interestingly, two of these SNPs, rs3772479 and rs2270569, are located in the FHIT and KIF9 genes, respectively, which have been reported to play an important role in inflammatory bowel disease (IBD) (Crohn’s disease being a type of IBD)." (PMID 37337586, 2023).
folate deficiency (2 papers, 2019 to 2023). A nutritional condition produced by a deficiency of FOLIC ACID in the diet. "Consistent with the induction of breakage at fragile sites (FS) upon folate deficiency, 24% of these alterations affected common FS, including the most active common FS genes FHIT, PARK2, and WWOX in the human genome." (PMID 30836646, 2019).
glioblastoma (2 papers, 2018 to 2024). The most malignant astrocytic tumor (WHO grade IV). "FHIT functions as a tumor suppressor, and changes in its gene expression alteration are implicated in the development of glioblastoma." (PMID 38584840, 2024).
head and neck cancer (2 papers, 2017 to 2018). A primary or metastatic malignant neoplasm affecting the head and neck. "al, several genes localized in 3p arm, known to be engaged in head and neck cancer appearance, e.g. FHIT or RASSF1A have been identified." (PMID 28710449, 2017). "Therefore, both high levels of APOBEC3B and APOBEC3A and low levels of FHIT expression may influence APOBEC mutagenesis in the head and neck cancer." (PMID 29642934, 2018).
high blood pressure (2 papers, 2018 to 2022). "Genes of ULK4 and FHIT have the highest number of hypertension-associated SNPs for genes mentioned in previous studies (Supplementary S5)." (PMID 35629146, 2022). "As over 40% of our French-Canadian IA cases were also affected with hypertension, we considered that rs1554600 in FHIT is possibly more likely to be a risk for hypertensive IA in French-Canadians." (PMID 29531279, 2018). "Additionally, the Fragile Histidine Triad Diadenosine Triphosphatase (FHIT) gene revealed 10 hypertension-associated SNPs with ≥3 log-p value, 1 of which was an SNP (rs57679512) with ≤4 log-p value." (PMID 35629146, 2022). "Based on the findings of this study and the functions of their encoded products, two genes (FHIT and CCDC80) are potentially relevant to IA with strong aggregation of familial IA cases with high blood pressure in the French-Canadian population." (PMID 29531279, 2018). "In addition, we identified 21 common genes that are shared between the GWAS and text mining analyses; of these, FNDC3B, FHIT, NPPC-DIS3L2, GLI2, and RBM47 genes are the most highly associated with hypertension." (PMID 35629146, 2022). "ULK4 and FHIT genes have 17 and 10 EH-associated SNPs, respectively, while FNDC3B, FHIT, NPPC-DIS3L2, GLI2, and RBM47 include SNPs that have a ≥4 log-p value association with hypertension in the studied cohort." (PMID 35629146, 2022).
hyperplasia (2 papers, 1999 to 2008). An abnormal increase in the number of cells in an organ or a tissue with consequent enlargement. "Expression of FHIT in adrenocortical adenoma is between carcinoma and hyperplasia." (PMID 18366613, 2008).
lung squamous cell carcinoma (2 papers, 2021 to 2023). "The FHIT gene is highly sensitive to environmental carcinogens, and its function is lost within the early pre-cancerous cells of lung squamous cell carcinoma." (PMID 37634038, 2023).
melanoma (2 papers, 2018 to 2022). A malignant, usually aggressive tumor composed of atypical, neoplastic melanocytes. "In melanoma cell lines, FHIT expression was associated with chemoresistance to the ALK inhibitor TAE684 (ρ = 0.621, padj = 0.0326, n = 38, Ntests = 26,610)." (PMID 29642934, 2018). "To assess FHIT activity as a therapeutic gene in melanoma, we generated a recombinant adenovirus encompassing the human cDNA of FHIT (AdFHIT)." (PMID 36289813, 2022). "In the following study, we observed that Fhit expression is significantly reduced in human melanoma cells, and their in vivo growth is blocked by a recombinant adenovirus carrying the FHIT gene." (PMID 36289813, 2022). "Colo38 melanoma cells were infected with Ad-FHIT and subsequently treated with DSP." (PMID 36289813, 2022).
metastatic disease (2 papers, 2013 to 2014). "Based on the results, the combinatorial presence of mutated Kras (codon 12) and methylated RASSF1A, FHIT and MGMT genes better characterize advanced tumor stage, metastatic disease, higher grade tumors and presence of lymphatic invasion than when considered separately." (PMID 23573237, 2013). "Overall, advanced tumor stage (97%), metastatic disease (100%), moderately to poorly differentiated tumors (84%) and presence of lymphatic invasion (92%) were more frequently observed in tumors with mutated Kras (codon 12) and methylated RASSF1A, FHIT and MGMT genes." (PMID 23573237, 2013).
Obesity (2 papers, 2016 to 2024). Accumulation of substantial excess body fat. "We observe significant associations of adiposity-OTU abundances with host genetic variants in the FHIT, TDRG1 and ELAVL4 genes, suggesting a potential role for host genes to mediate the link between the fecal microbiome and obesity." (PMID 27666579, 2016). "Therefore, it may have an indirect impact on FHIT adipose tissue gene expression in obesity through epigenetic regulation of FHIT expression." (PMID 27666579, 2016).
oral squamous cell carcinoma (2 papers, 2015 to 2017). "FHIT represents a further tumor suppressor gene that was associated with patients' prognosis in oral squamous cell carcinoma." (PMID 25633809, 2015).
osteosarcoma (2 papers, 2021 to 2022). A usually aggressive malignant bone-forming mesenchymal neoplasm, predominantly affecting adolescents and young adults. "Cell migration and invasion are closely associated with osteosarcoma metastasis, so we further examined the effect of FHIT overexpression on osteosarcoma cell migration and invasion." (PMID 34368151, 2021). "Rescuing its expression in osteosarcoma cells resulted in downregulation of N-cadherin and vimentin and upregulation of E-cadherin, which indicates that FHIT controls the switch between mesenchymal and epithelial markers." (PMID 35053522, 2022). "Of the six MRGs, FHIT is a potent tumor suppressor and its overexpression inhibited the migration, invasion, and metastasis of osteosarcoma by inhibiting EMT." (PMID 34368151, 2021). "Consistent with tumor suppressor function, FHIT was downregulated in osteosarcoma cells and human osteosarcoma samples." (PMID 34368151, 2021). "Of the six MRGs, FHIT was a potent tumor suppressor that was downregulated in osteosarcoma cell lines and tissue samples." (PMID 34368151, 2021). "To further explore the mechanism underlying the inhibitory effect of FHIT in osteosarcoma, we quantified the expression of EMT related-genes in FHIT-overexpressing osteosarcoma cells." (PMID 34368151, 2021). "Our results suggest a metastasis-inhibiting potential for FHIT in osteosarcoma, making it a therapeutic target worthy of further investigation." (PMID 34368151, 2021). "We found that FHIT overexpression reduced the migratory and invasive capacities of osteosarcoma cells." (PMID 34368151, 2021). "Of the six MRGs, FHIT is a well-documented tumor suppressor gene that is poorly defined in osteosarcoma." (PMID 34368151, 2021). "Consistently, FHIT mRNA and protein levels were significantly lower in osteosarcoma tissues than in adjacent normal tissues." (PMID 34368151, 2021). "FHIT overexpression decreased the mRNA and protein expression of Ki67, N-cadherin, and vimentin but increased expression of E-cadherin in osteosarcoma cells." (PMID 34368151, 2021). "FHIT overexpression inhibited osteosarcoma proliferation, migration, and invasion both in vitro and in vivo." (PMID 34368151, 2021). "We therefore quantified the expression of FHIT in normal osteoblasts (hFOB1.19 cells) and osteosarcoma cells including 143B, U2OS, MG63, and HOS." (PMID 34368151, 2021). "To explore the role of FHIT in osteosarcoma, we first upregulated FHIT expression in 143B and MG63 cells by lentivirus transfection and then detected the effect of FHIT overexpression on cellular proliferation." (PMID 34368151, 2021). "The effects of FHIT on osteosarcoma cell proliferation, migration, and invasion were examined in vitro and in vivo and the mechanism of action of FHIT in osteosarcoma metastasis further explored." (PMID 34368151, 2021). "qRT-PCR and western blotting showed that the mRNA and protein levels of FHIT were significantly lower in osteosarcoma cells compared to normal osteoblasts." (PMID 34368151, 2021). "Our six-MRG signature represents a novel and clinically useful prognostic biomarker for patients with osteosarcoma, and FHIT might represent a therapeutic target by reversing epithelial to mesenchymal transition." (PMID 34368151, 2021). "FHIT therefore represents a promising therapeutic target in osteosarcoma patients." (PMID 34368151, 2021). "Finally, we explored the effect of FHIT overexpression on osteosarcoma growth in vivo." (PMID 34368151, 2021). "However, little is known about the role of FHIT in osteosarcoma." (PMID 34368151, 2021). "Recently, a prognostic signature was found to include the gene fragile histidine triad diadenosine triphosphatase (FHIT), which is downregulated in osteosarcoma tissues versus normal osteoblasts." (PMID 35053522, 2022).
osteosarcoma (continued). "Expression of ABCA3, CTGF, and AMIGO2 were significantly higher in metastatic osteosarcoma samples compared to the primary osteosarcoma samples while the expression of PREB, FHIT, and EXOSC5 were significantly decreased in metastatic osteosarcoma samples." (PMID 34368151, 2021). "Mechanistically, FHIT overexpression repressed N-cadherin, vimentin, and Ki67 and increased the expression of E-cadherin, suggesting that its overexpression inhibits EMT in osteosarcoma cells." (PMID 34368151, 2021).
prostate carcinoma (2 papers, 2019 to 2022). A carcinoma that arises from epithelial cells of the prostate gland. "Investigating this gene pair, we found the reporting of FHIT-PTPRG fusion transcripts from kidney, liver, head and neck, lung, and prostate cancers." (PMID 30718424, 2019).
pulmonary hypertension (2 papers, 2020). Increased pressure within the pulmonary circulation due to lung or heart disorder. "Subsequently, the authors showed that pharmaceutical upregulation of FHIT prevented and reversed experimental pulmonary hypertension in a rat model." (PMID 33081265, 2020). "In agreement with this, FHIT−/− mice had more severe pulmonary hypertension and this was not reversed in normoxia, as opposed to in FHIT+/+ mice." (PMID 31538680, 2020).
serous ovarian carcinoma (2 papers, 2001 to 2008). "It seems that FHIT protein is playing an important role in the malignant course of serous ovarian cancer." (PMID 18366613, 2008).
skin tumors (2 papers, 2004 to 2012). "No promoter hypermethylation of FHIT or CDKN2A was identified in MCC, BCC, AK, or other skin tumors (data not shown)." (PMID 22768181, 2012).
urinary bladder tumors (2 papers, 2006 to 2012). "Among all the tumours showing a loss of FHIT activity, are tumours of the lower urinary tract, especially bladder tumours, one of the most frequent cancers in man." (PMID 16719907, 2006). "Knowledge of the molecular genomic organization of the FHIT locus as gathered from our work will be exploited also to study a peculiar feature of the urinary bladder tumors of cattle." (PMID 16719907, 2006). "However, FHIT downregulation has been recorded also in BPV induced bovine urinary bladder tumours which are composed of both epithelial and vascular (i.e. mesenchymal) tumours (personal observations)." (PMID 22424615, 2012).
viral infection (2 papers, 2023). "Moreover, epigenetic silencing of FHIT via methylation has been observed in 100% of PC samples with viral infection and the suppression of FHIT appears to activate tumorigenesis in hepatic lesions." (PMID 38069131, 2023). "Understanding how external factors affect the FHIT in early inflammatory or viral infection settings and how the FHIT inactivation facilitates cancer evolution and development are important for developing suitable prophylactic and therapeutic options for different cancer types." (PMID 36831487, 2023).
adrenocortical adenoma (1 paper, 2008). "When FHIT, Ki-67 and PCNA are all positive, adrenocortical adenoma is suggested." (PMID 18366613, 2008).